ADAM23 (ADAM metallopeptidase domain 23)
Description:
May play a role in cell-cell and cell-matrix interactions. This is a non-catalytic metalloprotease-like protein.
Synonyms: MDC-3; MDC3
Tractability: Antibody: UniProt places it where antibodies can reach, with high confidence; its Gene Ontology location is reachable by antibodies, with high confidence; UniProt predicts a signal peptide or a membrane-spanning region. PROTAC: its protein half-life has been measured.
Gene: Protein-coding gene on chromosome 2 (206,443,498 to 206,621,301, forward strand). Ensembl gene ENSG00000114948.
Subcellular location: Cell membrane; Secreted (Isoform Gamma)
Subcellular location (Human Protein Atlas): Nucleoplasm; Plasma membrane; Predicted to be secreted
Pathways (Reactome):
Developmental Biology: LGI-ADAM interactions
Gene Ontology:
Molecular function: protein binding; integrin binding; metalloendopeptidase activity; metallopeptidase activity
Biological process: central nervous system development; negative regulation of voltage-gated potassium channel activity; positive regulation of synaptic transmission; proteolysis; regulation of synapse assembly
Cellular component: trans-synaptic protein complex; plasma membrane; presynaptic membrane; extracellular region; glutamatergic synapse
Genetic constraint (gnomAD): Loss-of-function variants: 31 observed, 100.67 expected, observed/expected ratio (o/e) 0.31, 90% interval 0.23 to 0.42. The upper end of that interval is the gene's LOEUF score, 0.42, which puts it in group 1 of 6, group 1 being the genes least tolerant of losing a copy. Missense variants: 794 observed, 961.67 expected, observed/expected ratio (o/e) 0.83, 90% interval 0.78 to 0.88. Synonymous variants: 346 observed, 347.45 expected, observed/expected ratio (o/e) 1, 90% interval 0.91 to 1.09.
Homologues: Orthologues: chimpanzee ADAM23 (100% identical), pig ADAM23 (95% identical), macaque ADAM23 (95% identical), dog ADAM23 (95% identical), mouse Adam23 (94% identical), rabbit ADAM23 (91% identical), rat Adam23 (90% identical), guinea pig ADAM23 (82% identical), tropical clawed frog adam23 (72% identical), zebrafish adam23a (59% identical), Drosophila melanogaster kuz (16% identical), Caenorhabditis elegans sup-17 (15% identical). Paralogues in human: ADAM11 (46% identical), ADAM22 (46% identical), ADAM9 (28% identical), ADAM19 (27% identical), ADAM12 (26% identical), ADAM33 (26% identical), ADAM15 (25% identical), ADAM28 (24% identical), ADAM8 (24% identical), ADAM21 (23% identical), ADAM20 (23% identical), ADAM30 (23% identical), and 8 more.
Diseases named in the same sentence as ADAM23 in open-access papers:
ADAM23 is named in the same sentence as 53 diseases in open-access papers, as found by Europe PMC text mining. Sharing a sentence is not in itself a finding about the gene and the disease. The quoted sentences say what the papers report.
epilepsy (13 papers, 2012 to 2025). A brain disorder characterized by episodes of abnormally increased neuronal discharge resulting in transient episodes of sensory or motor neurological dysfunction, or psychic dysfunction. "The same risk haplotype was subsequently found to be associated with IE in four other breeds (Australian shepherd, Kromfohrländer, Labrador retriever, and whippet), proposing ADAM23 as a common risk gene for epilepsy with low penetrance." (PMID 36899667, 2023). "ADAM22 and ADAM23 genes were reported to be associated with progressive encephalopathy with epilepsy in human, and with genetic epilepsy in canine, respectively." (PMID 29237452, 2017). "Our results further support the role of ADAM23 in multiple breeds as a common risk gene for epilepsy with low penetrance." (PMID 28143391, 2017). "Our results further support the role of ADAM23 in multiple dog breeds as a common risk gene for epilepsy with low penetrance." (PMID 28143391, 2017). "Homozygosity for a two-SNP haplotype within the ADAM23 gene conferred the highest risk for epilepsy (p = 6.28×10−11, OR = 7.4)." (PMID 22457775, 2012). "Some studies have shown that ADAM23 gene is associated with epilepsy in mice and dogs." (PMID 32655475, 2020). "As we previously reported that ADAM23 is an important risk gene for canine IE, we also investigated whether ADAM23 plays a role in IE in an extended epilepsy collection, which consisted of eight additional dog breeds, and altogether 573 samples." (PMID 28143391, 2017). "LGI1, ADAM22, and ADAM23 are all genetically linked to epilepsy." (PMID 27066583, 2016). "A seven-fold epilepsy risk was found with the homozygous risk haplotype in the ADAM23 locus." (PMID 26084559, 2015). "ADAM23 binds two epilepsy-associated proteins, LGI1 and LGI2." (PMID 22457775, 2012). "LGI1 is mainly expressed in hippocampus and neocortex which is a transsynapsin secretory protein, it connects presynaptic epilepsy-related ADAM23 to postsynaptic ADAM22." (PMID 36316880, 2022). "To identify novel epilepsy genes, we performed genome-wide association (GWA) analyses in four new breeds, and investigated the association of the previously reported ADAM23 haplotype with the epilepsy phenotype in eight breeds." (PMID 28143391, 2017). "ADAM23 plays a role in synaptic transmission and interacts with known epilepsy genes, LGI1 and LGI2, and should be considered as a candidate gene for human epilepsies." (PMID 26084559, 2015). "Association of ADAM23 intronic SNP (BICF2P890779 at 18,123,961 bp) with epilepsy in 9 different breeds." (PMID 22457775, 2012). "We speculate that the anti-ADAM23 antibody interferes with ADAM23 function, resulting in epilepsy and widespread neuronal dysfunction." (PMID 40519920, 2025). "Mutation of these residues in both ADAM22 and ADAM23 disturbed the interaction with LGI1, while mutation of a nearby cysteine was identified in a patient with progressive encephalopathy, cortical atrophy, and severe epilepsy." (PMID 39050735, 2024). "ADAM23 was also highly expressed in the CNS and mouse knockout resulted in lethal epilepsy." (PMID 39050735, 2024). "A reduction in the ADAM23-mediated LGI1-stimulation of neurite outgrowth in the central nervous system was suggested to contribute to epilepsy, although other yet unknown ADAM-LGI-mediated alterations may exist." (PMID 26084559, 2015). "Furthermore, homozygous removal of Adam23 from mice results in a seizure disorder and even heterozygous mice have lowered seizure thresholds." (PMID 22457775, 2012). "ADAM23 interacts with known epilepsy proteins LGI1 and LGI2." (PMID 22457775, 2012). "However, the potential value of ADAM23 in the clinical is still unclear, so clinical studies are needed to explore whether ADAM23 protein is related to the incidence of epilepsy patients." (PMID 32655475, 2020). "This study emphasises the role of ADAM23 in canine epilepsy, and proposes a role for the LGI-ADAM pathway in epilepsy across species." (PMID 26084559, 2015).
epilepsy (continued). "The LGI1/ADAM23 (ligand-receptor) complex is considered “an exciting therapeutic target for human epilepsy” and the same can be stated about BRUNOL4, since alterations in this gene are involved not only in epilepsy but also in other neurological conditions, such as autism." (PMID 24278214, 2013).
breast carcinoma (7 papers, 2014 to 2022). "Studies have shown that a loss of expression of ADAM23 gene and its correlation with promoter methylation has been frequently reported in breast cancer, brain cancer, and pancreatic cancer." (PMID 31921385, 2019). "LGI1, a tumour suppressor, inhibits the growth and metastasis of breast cancer by target binding to ADAM23/AMAM22." (PMID 35003396, 2021). "For example, one study demonstrated that the survival of patients with breast cancer presenting CTCs with mesenchymal characteristics and no ADAM23 hypermethylation was similar to that of patients with no detectable CTCs and ADAM23 hypermethylation." (PMID 34644733, 2021).
Ataxia (4 papers, 2005 to 2015). Ataxia refers to impaired coordination of voluntary muscle movement. "It has been reported that the disruption of Adam23 gene in the mouse results in premature death associated with ataxia and tremor." (PMID 16504143, 2006). "It has been reported that ADAM23 protein is localised to the cell surface, interacts with alpha-v beta-3 integrin heterodimer and the disruption of ADAM23 gene in the mouse results in premature death associated with ataxia and tremor." (PMID 15876356, 2005). "A complete knockout of ADAM23 in mice results in ataxia, tonic-clonic seizures, failure to thrive and death within two weeks from birth." (PMID 26084559, 2015). "Adam23 mutants are smaller than wild type littermates and exhibit tremors and ataxia and Wars is uncharacterized." (PMID 22479196, 2012). "Mice lacking the Adam23 gene showed severe ataxia and tremor and died before weaning." (PMID 16504143, 2006).
Stroke (4 papers, 2022 to 2025). Sudden impairment of blood flow to a part of the brain due to occlusion or rupture of an artery to the brain. "The ADAM gene family, and particularly ADAM23 and members of this group, have also been implicated in worse prognosis, again reinforcing the value of these loci as potential biomarkers of stroke outcome and recovery." (PMID 40863347, 2025). "Significant genes like ADAM23 and GRIA1, implicated in neuronal excitability, are involved in the excitotoxic role in early post-stroke changes." (PMID 40863347, 2025). "A locus in ADAM23 has been shown to correlate with stroke outcome, and in our study multiple ADAM gene family members such as ADAM9, ADAM17, ADAM19 were associated with poor stroke outcomes." (PMID 36691064, 2023).
autoimmune encephalitis (3 papers, 2015 to 2025). Inflammation of the brain secondary to an immune response triggered by the body itself. "In this study, we show that using an IIF-CBA co-expressing LGI1 and ADAM23 all patients with LGI1 autoimmune encephalitis had LGI1 antibodies in CSF." (PMID 36591253, 2022). "We propose that anti-ADAM23 antibody, a previously overlooked autoantibody targeting the VGKC complex, may have diagnostic significance for autoimmune encephalitis." (PMID 40519920, 2025). "A retrospective analysis of nine serum and six CSF samples from patients with anti-LGI1 antibody-associated autoimmune encephalitis found no positivity for anti-ADAM23 antibodies, supporting its independent existence." (PMID 40519920, 2025). "LGI1 was also considered as a possible post-synaptic receptor for Caspr2 as it is recruited within the VGKC complex where it interacts with ADAM22 and ADAM23 and LGI1 is also involved in some autoimmune encephalitis." (PMID 26217189, 2015). "Anti-ADAM23 antibodies have not been previously reported in autoimmune encephalitis (AE)." (PMID 40519920, 2025).
autosomal dominant lateral temporal lobe epilepsy (3 papers, 2012 to 2020). "The interaction of LGI1 with ADAM22 and ADAM23 makes an important impact on the molecular mechanism of autosomal dominant lateral temporal lobe epilepsy (ADLTE)." (PMID 32655475, 2020). "Mutations in ADAM23 have not been found in epileptic patients, but it interacts with LGI1, a gene associated with familial temporal lobe epilepsy-1 (ETL1) in human and with LGI2, which is the causative gene for benign focal epilepsy in dogs." (PMID 22457775, 2012).
lung carcinoma (3 papers, 2017 to 2024). "Studies indicate that in lung cancer cells, ADAM23 interacts with integrin αvβ3 to exert inhibitory effects on cancer progression, suggesting that downregulation of ADAM23 in SP cells may contribute to enhancing the phenotype of tumor stem cells by promoting the activity of integrin αvβ3." (PMID 39239559, 2024).
Obesity (3 papers, 2018 to 2024). Accumulation of substantial excess body fat. "Multivariate analysis showed that the effect for ADAM23 remained significant after adjusting for the indirect effects of obesity, diabetes mellitus and smoking." (PMID 38985358, 2024).
psoriasis (3 papers, 2009 to 2024). An autoimmune condition characterized by red, well-delineated plaques with silvery scales that are usually on the extensor surfaces and scalp. "We observed an increased expression of GPRIN1 and ADAM23 at the gene and protein level in PPP/PPPP as compared to psoriasis and/or normal acral skin." (PMID 27152848, 2016). "Some of the genes found to be commonly upregulated in psoriasis and skin SCC, such as ADAM23, Krt16 (cytokeratin 16) and IVL (involucrin), were also found to be upregulated in 3 week TPA treated skin (data not shown)." (PMID 19432991, 2009).
brain tumor (2 papers, 2008 to 2023). "We showed that ADAM23 depletion leads to brain tumors with more complex morphology (7% higher FD) and with low intracranial pressure (40% lower MLS), leading us to infer that ADAM23low astrocytomas are better space-filling tumors." (PMID 38024245, 2023).
encephalitis (2 papers, 2021 to 2025). An acute inflammatory process affecting the brain parenchyma. "However, given that anti-ADAM23 antibody-associated encephalitis remains very rare, accumulating more real-world cases is essential to gain a deeper understanding and better treatment experience for IgG4-related autoimmune diseases." (PMID 40519920, 2025).
epithelial ovarian cancer (2 papers, 2021 to 2026). "Reports suggest that ADAM-23 is also expressed in multiple tumor types whereas in epithelial ovarian cancer (EOC) a lower expression level of ADAM-23 is seen." (PMID 34912809, 2021).
esophageal cancer (2 papers, 2021 to 2024). A primary or metastatic malignant neoplasm involving the esophagus. "ADAM23 exhibits a tumor suppressor role and was found to promote tumor cell death and reduce cell proliferation by promotion of ferroptosis in esophageal cancer." (PMID 38985358, 2024).
gastric cancer (2 papers, 2020 to 2021). A primary or metastatic malignant neoplasm involving the stomach. "It was previously reported that low expression or hypermethylation of ADAM23 was associated with poor prognosis in lung, ovarian, breast, and gastric cancers." (PMID 35003396, 2021). "The study found that six genes (MINT25, RORA, GDNF, ADAM23, PRDM5, MLF1) presented differential methylation between gastric cancer and normal mucosa in the training and test population." (PMID 32489454, 2020).
Alzheimer disease (1 paper, 2023). A progressive, neurodegenerative disease characterized by loss of function and death of nerve cells in several areas of the brain leading to loss of cognitive function such as memory and language. "We identified gene expression signatures associated with Alzheimer’s disease (AD) and we found that ADAM23 depletion increases GS activity in astrocytoma cells." (PMID 38024245, 2023).
astrocytomas (1 paper, 2023). "Considering the large spectrum of human cancers associated with ADAM23 silencing and its major expression in the brain, it is likely that ADAM23 downregulation is associated with the activation of malignant programs in astrocytoma cells." (PMID 38024245, 2023). "Here we showed that the gene ADAM23 is downregulated in diffuse astrocytoma (Grade 2–4) cells compared with the normal brain tissues and that the invasive behavior of astrocytoma cells is inhibited by ADAM23." (PMID 38024245, 2023). "The role of ADAM23 in the infiltrative behavior of astrocytomas was evaluated using 21 preoperative astrocytoma data sets included in the TCIA-TCGA repositories." (PMID 38024245, 2023). "Taken together, these data suggest a mechanism where GS is activated by the downregulation of ADAM23 in astrocytoma cells." (PMID 38024245, 2023). "We integrated in vitro and in vivo functional assays, RNA sequencing, clinical, and expression information from public data sets to investigate the role of ADAM23 expression coupling astrocytoma’s growth and motility." (PMID 38024245, 2023). "ADAM23 downregulation resulted in increased infiltration, reduced tumor growth, and improved overall survival in astrocytomas." (PMID 38024245, 2023). "So, reviewing the literature for ADAM23 promoter methylation patterns in other malignancies, we can suggest that ADAM23 may be also gradually and progressively downregulated during astrocytoma progression facilitating the infiltrative phenotype." (PMID 38024245, 2023). "Our findings reveal a role for ADAM23 in regulating the balance between cell proliferation and invasiveness in astrocytoma cells, proposing GS inhibition as a therapeutic option in ADAM23 low-expressing astrocytomas." (PMID 38024245, 2023). "Finally, GS ablation in ADAM23-low astrocytomas induced a significant inhibitory effect on the invasive programs." (PMID 38024245, 2023). "Next, to determine whether ADAM23 levels might be a biomarker of improved survival in human astrocytomas, we used the clinical and expression information from the TCGA and CGGA cohorts." (PMID 38024245, 2023). "Moreover, depletion of endogenous ADAM23 in GSCs results in increased brain infiltration and slow-growing tumors, prolonging survival in patients with astrocytoma and murine models owing to reduced cerebral herniation." (PMID 38024245, 2023). "ADAM23 depletion leads to 140% increase in cerebral Aβ-amyloidosis and up to 190% increase in cytoplasmic NICD compared with ADAM23hi astrocytoma cells." (PMID 38024245, 2023). "Independent of the tumor grade, all astrocytomas displayed a marked decrease in ADAM23 expression compared with NNB (P < .0001)." (PMID 38024245, 2023). "Next, to assess the role of ADAM23 expression in astrocytomas, we examined ADAM23 levels in a panel of GSC and non-GSC GBM cell lines (P < .001)." (PMID 38024245, 2023). "Our discoveries suggest that ADAM23 downregulation in astrocytoma cells activates GS promoting the proneural-mesenchymal transition (PMT) and providing an experimental basis for the use of GSI for astrocytoma patients with ADAM23low tumors." (PMID 38024245, 2023). "To evaluate ADAM23 expression in CNS tumors, we measured ADAM23 mRNA levels using qRT-PCR in the non-neoplastic brain (NNB) and 143 WHO Grades 2–4 astrocytomas from the HC cohort." (PMID 38024245, 2023). "Our data support that ADAM23 downregulation in GSCs and non-GSC astrocytoma cells promotes diffuse astrocytoma invasiveness by increasing GS activity." (PMID 38024245, 2023).
colorectal cancer (1 paper, 2021). A primary or metastatic malignant neoplasm that affects the colon or rectum. "The silencing or decreased methylation of ADAM23 gene often associated with advanced disease and metastasis in different types of tumours, including colorectal cancer." (PMID 33949771, 2021).
diffuse astrocytoma (1 paper, 2023). A low-grade (WHO grade II) astrocytic neoplasm. "Our results also suggest the possibility of using GSI as a new line of targeted therapeutic agents for diffuse astrocytomas with intrinsic low ADAM23 expression levels." (PMID 38024245, 2023). "ADAM23 expression was significantly lower in diffuse astrocytomas compared with NNB (P < .001)." (PMID 38024245, 2023).
embryonic carcinoma (1 paper, 2017). "Downregulation of ADAM23 drives embryonic carcinoma P19 cells to differentiate into neuroectodermal cells, where ADAM23 suppresses neuronal differentiation via its disintegrin domain by inhibiting P27KIP1 function." (PMID 28828010, 2017). "In an embryonic carcinoma cell line of P19 cells, downregulation of ADAM23 promotes cell differentiation into neurons, with or without retinoic acid treatment, in in vitro aggregated culture, but not in monolayer cell culture." (PMID 28828010, 2017).
esophageal squamous cell carcinoma (1 paper, 2023). Esophageal squamous cell carcinoma (ESCC) is a type of esophageal carcinoma (EC) that can affect any part of the esophagus, but is usually located in the upper or middle third. "Overexpression of ADAM23 (ADAM Metallopeptidase Domain 23) has been experimentally shown to promote ferroptosis in esophageal squamous cell carcinoma and is expected to play a role in future cancer therapy." (PMID 38127902, 2023).